AKIRIN1 (akirin 1)
Description:
Molecular adapter that acts as a bridge between proteins, and which is involved skeletal muscle development (By similarity). Functions as a signal transducer for MSTN during skeletal muscle regeneration and myogenesis (By similarity). May regulate chemotaxis of both macrophages and myoblasts by reorganising actin cytoskeleton, leading to more efficient lamellipodia formation via a PI3 kinase dependent pathway (By similarity). In contrast to AKIRIN2, not involved in nuclear import of proteasomes.
Synonyms: C1orf108; FLJ12666; STRF2
Tractability: PROTAC: ubiquitination databases record sites on it.
Gene: Protein-coding gene on chromosome 1 (38,991,272 to 39,006,059, forward strand). Ensembl gene ENSG00000174574.
Subcellular location: Nucleus
Subcellular location (Human Protein Atlas): Nucleoplasm; Nuclear membrane
Gene Ontology:
Molecular function: protein binding; transcription coregulator activity
Biological process: myoblast migration involved in skeletal muscle regeneration; negative regulation of satellite cell differentiation; negative regulation of skeletal muscle satellite cell proliferation; positive regulation of lamellipodium assembly; positive regulation of macrophage chemotaxis; positive regulation of myoblast differentiation; positive regulation of transcription by RNA polymerase II
Cellular component: nucleoplasm; nucleus; chromatin
Genetic constraint (gnomAD): Loss-of-function variants: 4 observed, 21.04 expected, observed/expected ratio (o/e) 0.19, 90% interval 0.093 to 0.44. The synonymous counts are far from expectation, so gnomAD's model fits this gene poorly and the ratio says little. Missense variants: 243 observed, 213.26 expected, observed/expected ratio (o/e) 1.14, 90% interval 1.02 to 1.27. Synonymous variants: 125 observed, 83.21 expected, observed/expected ratio (o/e) 1.5, 90% interval 1.3 to 1.74.
Homologues: Orthologues: chimpanzee AKIRIN1 (100% identical), macaque AKIRIN1 (100% identical), guinea pig AKIRIN1 (96% identical), rat Akirin1 (94% identical), mouse Akirin1 (93% identical), pig AKIRIN1 (81% identical), tropical clawed frog akirin1 (71% identical), zebrafish akirin1 (68% identical), Drosophila melanogaster akirin (34% identical), Caenorhabditis elegans akir-1 (31% identical). Paralogues in human: AKIRIN2 (59% identical).
Diseases named in the same sentence as AKIRIN1 in open-access papers:
AKIRIN1 is named in the same sentence as 6 diseases in open-access papers, as found by Europe PMC text mining. Sharing a sentence is not in itself a finding about the gene and the disease. The quoted sentences say what the papers report.
Atrophy (1 paper, 2014). Any weakening or degeneration, especially through lack of use. "Therefore, we posit that MSTN-induced atrophy observed in the current study is likely linked to the MSTN-induced down-regulation in Akirin-1/Mighty mRNA." (PMID 25132809, 2014).
kidney injury (1 paper, 2024). Trauma to the kidney. "However, details on the molecular interactions of Akirin‐1 remain incompletely understood, and it is not clear whether it plays a role in the IR‐induced kidney injury." (PMID 39188701, 2024).
kidney transplant (1 paper, 2024). A surgical procedure in which one or both kidneys from a donor are implanted into a recipient. "In summary, these findings suggest that Akirin1, which prominently induces ferroptosis, is a pivotal biomarker and target for early diagnosis and treatment of graft kidney IRI and DGF after kidney transplant." (PMID 39188701, 2024).
Sepsis (1 paper, 2019). Sepsis is defined as life-threatening organ dysfunction caused by a dysregulated host response to infection. "This analysis yielded highly similar expression levels for four of our five candidate reference genes in SIRS and sepsis NK cells, namely, AKIRIN1, PPP6R3, TAX1BP1, and ADRBK1." (PMID 31075840, 2019). "Here, we demonstrated highly similar AKIRIN1 expression levels in both NK cells and granulocytes from patients with SIRS and sepsis at ICU admission as well as in granulocytes from healthy donors after in vitro LPS challenge." (PMID 31075840, 2019). "The major observation of this study was that expression levels of AKIRIN1 determined in NK cells and granulocytes isolated from peripheral blood were highly similar in patients admitted to the ICU with SIRS compared to sepsis." (PMID 31075840, 2019). "Microarray data from our discovery set suggested approximately 20% lower AKIRIN1 expression levels in both presurgical and SIRS granulocytes each compared to sepsis." (PMID 31075840, 2019). "As a potential new reference gene in NK cells and granulocytes in infectious and inflammatory diseases, AKIRIN1 may improve our pathomechanistic understanding of SIRS and sepsis and help identifying new sepsis biomarkers." (PMID 31075840, 2019). "In conclusion, we propose to include AKIRIN1 in future screens of canonical reference genes for normalizing gene expression in peripheral blood NK cells and granulocytes in patients with SIRS and sepsis." (PMID 31075840, 2019). "We introduce AKIRIN1 as the first potential reference gene for future differential gene expression analysis in NK cells and granulocytes from critically ill patients with SIRS and sepsis." (PMID 31075840, 2019). "Likewise, in vitro LPS treatment altered AKIRIN1 expression in neutrophils neither from patients with sepsis-induced ALI nor from healthy volunteers." (PMID 31075840, 2019). "However, we determined highly similar AKIRIN1 expression also in SIRS and sepsis granulocytes and no change by in vitro LPS challenge in granulocytes from healthy donors." (PMID 31075840, 2019).
kidney (1 paper, 2024). "We subsequently detected that, consistent with the effects of Akirin1‐knockout, supplementation with exogenous UM‐EVs also attenuated IRI‐induced graft kidney injury in morphology and function, as indicated by H&E staining and the SCr and BUN concentrations." (PMID 39188701, 2024).
AKIRIN1 also shares sentences with these, for which no sentence is quoted: sarcopenia (1 paper).